VWF (von Willebrand factor)
Diseases named in the same sentence as VWF in open-access papers (continued):
Sharing a sentence is not in itself a finding about the gene and the disease.
cancer (continued). "We made several novel observations that together define a critical role of vWF in promoting cancer metastasis." (PMID 29362409, 2018). "Scans with an IVIS Lumina Imaging System showed that mice infused with vWF-overexpressing cells (that also expressed GFP as a tracer) had faster cancer grafts than those receiving sham-transfected cells." (PMID 29362409, 2018). "Up-regulated expression of vWF was observed as early as 2 weeks after cancer cell inoculation and progressively increased through the later stages of metastases development." (PMID 29788918, 2018). "More importantly, a substantial amount of vWF became cell-bound, being primarily mediated by β3 integrin, which has been demonstrated to express on the surface of cancer cells and to mediate cancer metastasis." (PMID 29362409, 2018). "The graft enhancement was also blocked when the vWF-overexpressing cells were pre-incubated with either an antibody against human vWF, which targets only cancer cell-derived vWF or an antibody against both human and mouse CD42b, the platelet receptor for vWF." (PMID 29362409, 2018). "The findings also suggest that vWF is not only a biomarker but a mediator for cancer metastasis and a new therapeutic target for cancer." (PMID 29362409, 2018). "We have also shown that vWF secreted from cultured cancer cells was detected in solution and on cell surface." (PMID 29362409, 2018). "Taken together, we demonstrate that vWF expression in ECs of LAC is elevated by the cancer cell-derived secretome through enhanced GATA3-mediated transcription." (PMID 29299165, 2017). "Based on these results, we propose that acquiring VWF expression confers a metastatic advantage to subpopulations of cancer cells, through enhancing their platelet interaction, adhesion capacity, migration, and extravasation capability." (PMID 28035064, 2017). "As expected, levels of expression from VWF expressing cancer cells were significantly lower than that expressed by human umbilical vein endothelial cells (HUVECs), which are the cell types that normally express VWF." (PMID 28035064, 2017). "Analyses of the mechanism of transcriptional activation of the VWF in cancer cells demonstrated a pattern of trans-activating factor binding and epigenetic modifications consistent overall with that observed in ECs." (PMID 28035064, 2017). "In a non-cancer model, vWF biosynthesis was markedly increased in ECs that regenerated from aorta balloon injuries." (PMID 29299165, 2017). "VWF expressing cancer cells (shown by dashed arrows) were distinguished from VWF expressing vascular endothelial cells (shown by solid arrow) and quantified by an expert pathologist." (PMID 28035064, 2017). "Endothelial monolayer adhesion, transmigration and extravasation capacities of VWF expressing cancer cells were shown to be enhanced compared to non-VWF expressing cells, and were significantly reduced as a result of VWF knock down." (PMID 28035064, 2017). "A role for VWF in cancer metastasis has long been postulated but evidence supporting both pro- and anti-metastatic roles for VWF has been presented." (PMID 28035064, 2017). "We identified characteristics of VTE, including VWF-platelet aggregates and vessel occlusion, in multiple organs distal to the primary tumor that suggest a plausible mechanism for thrombosis in cancer patients." (PMID 27602496, 2016). "However, it should be emphasized that VWF is an acute phase inflammatory marker and it is, therefore, often difficult to establish exactly whether raised levels are causal or simply an epiphenomenon of the underlying cancer‐associated inflammatory process." (PMID 27236861, 2016). "Further experimental studies are also needed to unravel the molecular mechanisms linking ABO blood type, VWF, and cancer development." (PMID 25592962, 2015). "The integral link between tumorigenesis and angiogenesis supports a potential role for vWF in cancer." (PMID 25886574, 2015).
cancer (continued). "Some of these cancer-related genes were associated with processes occurring in the extracellular matrix and related to DCN: CXCR4/CXCL12 axis, SELP, vWF, COL3A1, SCARA, SPARCL1." (PMID 26437222, 2015). "Impaired von Willebrand factor cleaving activity of ADAMTS-13 was also demonstrated in patients with metastasizing malignant tumors." (PMID 22206706, 2011). "von Willebrand factor (vWF) promotes platelet adhesion during thrombus formation and elevated vWF levels have been detected in various cancers." (PMID 20074349, 2010). "The link between VWF and cancer biology is complex and incompletely understood." (PMID 41536292, 2026). "From these clusters, five major cell types were identified via classical cell markers, including T cells (CD3E, CD8A, CD3D), B cells (CD19, MS4A1, CD79A), myeloid cells (CD14, CD68, LYZ), endothelial cells (PECAM1, VWF, CDH5) and cancer-associated fibroblasts (CAFs) (ACTA2, FAP, PDGFRB)." (PMID 39941131, 2025). "Interestingly, IHC in our study showed a significant increase of vWF expression in LVO clots from patients with active cancer compared to controls." (PMID 39760182, 2025). "Consistently, it has been evidenced that elevated VWF levels in cancer patients may not only lead to cancer-related clotting disorders but can also mediate cancer progression and metastasis." (PMID 40740229, 2025). "Such interactions between VWF multimers may happen when VWF secreted from EC, platelets, cancer cells, or within the same VWF multimer." (PMID 39282473, 2024). "For example, the stromal subset consisted of endothelial cells identified by expressions of VWF, PECAM1 and KDR, pericytes with high RGS5, ACTA2, and COL4A1 expressions, and cancer-associated fibroblasts (CAFs) identified by significant expressions of COL1A1, DCN and LUM." (PMID 38925650, 2024). "Answering these questions will improve our understanding of VWF function in cancer metastasis as well as the contribution of fluid mechanics in these processes, which can potentially provide important insights into developing new anti-metastatic strategies to treat cancer." (PMID 39282473, 2024). "Under normal blood flow, circulating VWF remains in a compact conformation, which could possibly prevent it from interacting with cancer cells." (PMID 39282473, 2024). "Inhibition of cancer cell-derived VWF expression can thus reduce cancer cell metastasis." (PMID 39282473, 2024). "Such hydrodynamic forces could possibly induce VWF extension and initiate its binding to cancer cells." (PMID 39282473, 2024). "Patients with cancer have higher vWF levels, and these can vary among different ABO blood types." (PMID 38950056, 2024). "The multimeric structure of VWF allows multiple binding sites of one VWF molecule to interact with many different ligands from other cells or biomolecules, such as cancer cells, platelets, EC, and other VWF multimers, to have different functions at the same time." (PMID 39282473, 2024). "Furthermore, von Willebrand factor can facilitate binding between platelet GPIbα and GPIbα-like motifs on cancer cells." (PMID 39654896, 2024). "Here, we will focus on the contribution of VWF in interacting with platelets, EC, cancer cells, and several of their receptor proteins, such as platelet GPIbα, P-selectin, ανβ3 and αIIbβ3 integrins, and glycocalyx, in cancer cell adhesion to the EC surface." (PMID 39282473, 2024). "Thus, VWF attached on a surface, especially in the cases of vascular injury or stenosis, potentially plays a more important role in cancer migration than circulating plasma VWF under the same flow condition." (PMID 39282473, 2024). "Certain cancer cells may express the hemostatic glycoprotein Von Willebrand factor (VWF) as well for their own benefits." (PMID 37583933, 2023). "VWF is a highly complex molecule that has a role in both physiological and pathological hemostasis, as well as being a mediator of inflammation, angiogenesis and cancer biology." (PMID 35327035, 2022).
cancer (continued). "vWF potentiates TCIPAwhile inhibition of this factor reduces platelet–cancer cell interactions." (PMID 35814405, 2022). "It is considered that vWF is one of the major platelet adhesion ligands that may also mediate cancer progression and metastasis." (PMID 35814405, 2022). "The main barrier to utilizing VWF as a potential target for cancer therapy is the relative infancy of our understanding of how VWF and ADAMTS13 mechanistically affect malignancy and metastasis, and the heterogeneity and inconsistencies reported in the literature." (PMID 35327035, 2022). "Although characterization of vascular markers was minimal, including only Collagen IV and VWF, the functional results (the fact that cancer cells find the decellularized capillary structures) confirm that the required proteins are still present after the decellularization." (PMID 35203480, 2022). "VWF has also been studied as a potential biomarker for cancer treatment response outcomes." (PMID 35327035, 2022). "Interestingly, 7 of the top 10 oncogene candidate protein-coding genes identified (e.g., FSTL1, VCAM1, VWF) were shown in other cancer types to promote cell migration, invasion, or metastasis." (PMID 36359790, 2022). "In this process, VWF is important in potentiating the cancer-cell platelet aggregation." (PMID 33571850, 2021). "However, emerging evidence suggests that some cancer cells, for example the gastric adenocarcinoma and osteosarcoma cells, also express VWF." (PMID 33571850, 2021). "Independent of its contribution to haemostasis, accumulating evidence suggests that VWF may also play several important roles in cancer metastasis." (PMID 33571850, 2021). "For example, VWF may orchestrate cancer dissemination via an array of pathways, including angiogenesis and hypercoagulopathy." (PMID 33571850, 2021). "It is tempting to speculate that autophagy plays a central role in mediating cancer-related thrombosis and metastasis by regulating vWF release from the activated endothelium." (PMID 33365273, 2020). "It is possible that cancer cells might somehow prepare the vascular wall for metastasis by increasing vWF expression on the activated endothelium, thus facilitating the mentioned adhesion, later followed by aggregation." (PMID 32191918, 2020). "Several studies have also demonstrated increased plasma vWF levels in cancer patients." (PMID 33292287, 2020). "High VWF levels were significantly associated with the risk of developing VTE in cancer patients, whereas ADAMTS‐13 was not." (PMID 31294335, 2019). "von Willebrand factor (vWF) is one of the major platelet adhesion ligands that could potentially regulate cancer development and metastasis." (PMID 29362409, 2018). "This experimental model was chosen specifically to investigate whether vWF promotes the extravagation of circulating cancer cells through endothelial cells of the vessel wall." (PMID 29362409, 2018). "Third, the finding that vWF enhanced the homotypic interaction among cancer cells and heterotypic interactions with platelets and endothelial cells led to the hypothesis that vWF promotes blood-born cancer metastasis." (PMID 29362409, 2018). "Interestingly, vWF did not increase in the pulmonary endothelium, but was even lower in the late stage of metastasis formation compatible with a possible involvement of vWF in cancer cell metastasis to the lungs." (PMID 29788918, 2018). "However, the aggregation of BGC823 cells was enhanced by serum and further increased with platelet-rich plasma (PRP) in a vWF-dependent manner, strongly indicating that plasma vWF and platelets enhanced the cancer cell aggregation." (PMID 29362409, 2018). "The vWF expression quantified by antibody binding intensity was stronger in poorly differentiated cancerous tissues than in moderately differentiated and well-differentiated cancer cells." (PMID 29362409, 2018).
cancer (continued). "Moreover, vWF was expressed in OS cell line SAOS2 and increased the adhesion capacity of SAOS2 cells to endothelial monolayer, causing increased cancer cell extravasation and transmigration." (PMID 30279208, 2018). "The surface-bound vWF could regulate the rate of metastasis by promoting cancer cells to self-aggregate and adhere to platelets and endothelial cells (, 4)." (PMID 29362409, 2018). "Our data further suggest that, although plasma vWF may have contributed to the formation of BCG823 cell aggregates, the pulmonary metastasis was primarily mediated by cancer-bound vWF." (PMID 29362409, 2018). "Moreover, the high levels of plasma vWF were detected in patients with glioblastoma, acute lymphoblastic leukemia, colorectal cancer, urinary bladder cancer, and other types of cancers." (PMID 30279208, 2018). "To determine whether the increased endothelial adhesion and transmigration activity of VWF-expressing cancer cells translates into an increased potential for extravasation, we performed the ex ovo (chorioallantoic membrane) assay." (PMID 28035064, 2017). "Taken together, our ex ovo and in vivo experiments strongly support the hypothesis that acquisition of VWF expression confers an enhanced extravasation capability to cancer cells." (PMID 28035064, 2017). "Consistent with this hypothesis, anti-VWF antibodies were shown to decrease metastatic activities of some cancer cell lines passaged as xenotransplants in mice, and inhibited adhesion of a colon cancer cell line to ECs in a co-culture adhesion assay." (PMID 28035064, 2017). "Discordant observations regarding the role of VWF in cancer metastasis may be, at least partly, attributed to the focus of investigations on ECs and platelets as the source of VWF." (PMID 28035064, 2017). "In addition to its major role in hemostasis, VWF has been reported to participate in the immune response, inflammation, angiogenesis and cancer metastasis." (PMID 28035064, 2017). "These contradictory observations may be reconciled if we consider a distinct role for VWF when expressed by ECs compared to that acquired by cancer cells." (PMID 28035064, 2017). "We explored the mechanism by which VWF expression is acquired in cancer cells." (PMID 28035064, 2017). "Such cancer cells will have enhanced survival and metastasis if presented to VWF knockout mice." (PMID 28035064, 2017). "Furthermore, if a population of cancer cells expresses VWF and this contributes to their metastatic role, they will continue to metastasize in the VWF knockout mice." (PMID 28035064, 2017). "To determine whether increased endothelial-adhesiveness of VWF-expressing cancer cells leads to increased transmigration across an endothelial barrier, we performed the transwell migration assay as described in Methods." (PMID 28035064, 2017). "Our analyses demonstrated that in all these processes, VWF expression confers an increased ability of cancer cells that express this protein to adhere to endothelial monolayers and platelets, processes that may contribute to an increased metastatic potential." (PMID 28035064, 2017). "Regarding the role of VWF in cancer metastasis, it was hypothesized that VWF participates in adhesion of cancer cells to platelets and endothelial surfaces, thus facilitating extravasation and promoting metastasis." (PMID 28035064, 2017). "We propose that this hypothesis may bring together seemingly contradictory evidence regarding the role of VWF (as pro or anti-metastatic) in cancer metastasis." (PMID 28035064, 2017). "Our results provide strong evidence for the role of these regulatory components in establishing VWF transcription and present them as potential targets for future development of therapies towards regulation of VWF expression in cancer cells, and interference with the metastatic process." (PMID 28035064, 2017).
cancer (continued). "We hypothesized that the role of VWF in cancer metastasis is influenced by its cellular origin and that cancer cell acquisition of VWF expression may contribute to enhanced metastatic potential." (PMID 28035064, 2017). "Plasma VWF, mainly deriving from endothelial cells, is often raised in patients with cancer and this may be due to an increased release in the neoplastic microenvironment where neoangiogenesis is a common feature." (PMID 27236861, 2016). "Because it is generally accepted that platelets contribute to each step in metastasis formation, VWF may promote cancer dissemination and spread." (PMID 27602496, 2016). "We hypothesized that cancer-related VTE is a consequence of VWF-mediated platelet aggregation in organs distal to the primary tumor." (PMID 27602496, 2016). "However, certain aggressive cancer cells are able to escape vWF-induced cell death through production of the protease ADAM28 that can counterbalance the pro-apoptotic function of vWF." (PMID 26306290, 2015). "Since physiological levels of vWF can induce cancer cell apoptosis, an attractive strategy could be to stimulate endothelial secretion of vWF by a pharmacological intervention, such as dDAVP infusion, aimed at increasing host resistance to metastasis." (PMID 26306290, 2015). "Lack of ADAMTS13’s catalytic activity in cleaving vWF was associated with progression of various cancers." (PMID 24213506, 2012). "After binding with platelets and cancer cells, VWF experiences higher forces applied by these cells under flow, which may in turn activate more monomers in VWF strings to recruit more platelets and cancer cells and promote cancer cell adhesion to the EC surface." (PMID 39282473, 2024). "Using VWF as a “bridge”, cancer cells and platelets may thus interact with EC through GPIbα, P-selectin, ανβ3 and αIIbβ3 integrins, and/or glycocalyx to facilitate cancer cell adhesion to the EC surface." (PMID 39282473, 2024). "Here we found a 4.5 times higher risk (CI 0.9535 to 20.93; p: 0.047) for cancer recurrence in patients if the baseline value of factor VIII:C was above the median of 175% and a 12.5 times higher risk (CI 2.562 to 60.58; p: 0.002) if the baseline vWF ag was above the median of 127%." (PMID 39487855, 2024). "Numerous reports of various malignancy-associated changes in VWF and ADAMTS13 levels have inspired this current review into exploring these documented changes and potential associations with bleeding and thrombotic phenomena as well as possible links to cancer metastasis and prognosis." (PMID 35327035, 2022). "Importantly, VWF is a major determinant of VTE in cancer patients." (PMID 33571850, 2021). "Interestingly, certain aggressive cancer cells are not susceptible to the pro-apoptotic function of VWF." (PMID 33571850, 2021). "They suggested that, on the one hand, cancer cells that do not express VWF may be susceptible to the pro-apoptotic effect of VWF." (PMID 34572000, 2021). "Such cancer cells might exhibit enhanced survival and metastasis in VWF knockout mice." (PMID 34572000, 2021). "Furthermore, VWF has been recently shown to participate in a number of other physiological and pathophysiological processes, such as inflammation, angiogenesis, and cancer metastasis, which are the subject of many recent excellent reviews and will not be discussed here." (PMID 34575297, 2021). "However, in addition to its hemostatic properties, recent evidence suggests that VWF may have additional role(s) in modulating cancer cells biology." (PMID 33800224, 2021). "Interestingly, recent evidence suggests that VWF is also synthesised and released by cancer cells." (PMID 33571850, 2021). "Since the relation in the size of UL-vWF multimers via ADAMTS-13 is a relevant mechanism of thrombosis in cancer patients, reduced ADAMTS-13 levels as well as high plasma vWF:Ag levels, causing a high vWF:Ag/ADAMTS-13 ratio, may serve as independent predictive factors." (PMID 33292287, 2020).